TCAM1P (testicular cell adhesion molecule 1, pseudogene)
Synonyms: formerly TCAM1
Gene: Transcribed unitary pseudogene on chromosome 17 (63,857,141 to 63,862,889, forward strand). Ensembl gene ENSG00000240280.
Diseases named in the same sentence as TCAM1P in open-access papers:
TCAM1P is named in the same sentence as 9 diseases in open-access papers, as found by Europe PMC text mining. Sharing a sentence is not in itself a finding about the gene and the disease. The quoted sentences say what the papers report.
cervical (1 paper, 2022). "In this study, we first proposed TCAM1P as a testis/cancer-specific pseudogene, and used a series of experimental data to verify its relationship with HPV, and analyzed its diagnosis value of high-grade cervical lesions and the mechanism of their high expression in cervical cancer." (PMID 35016697, 2022).
cervical cancer (1 paper, 2022). A primary or metastatic malignant neoplasm involving the cervix. "This suggested the potential clinical value of TCAM1P in cervical cancer screening and targeted therapy, but more evidence is needed." (PMID 35016697, 2022). "In our study, we also found that the expression of TCAM1P in HPV-positive cervical cancer is higher than HPV-negative cervical cancer at the tissue and cell levels." (PMID 35016697, 2022). "Otherwise, TCAM1P promote proliferation through regulating cell cycle and DNA replication, but more evidence needs to be provided to reveal the mechanism by which TCAM1P plays a role in cervical cancer." (PMID 35016697, 2022). "Survival analysis results showed that higher TCAM1P is a protective factor for patients with cervical cancer." (PMID 35016697, 2022). "In our study, we found that EIF4A3 regulated the expression of TCAM1P, which means high expression of TCAM1P in cervical cancer is regulated by EIF4A3." (PMID 35016697, 2022). "Results showed that only TCAM1P is the common DEPGs and the expression level of TCAM1P in cervical cancer is higher than normal cervix tissue in all datasets that detect TCAM1P." (PMID 35016697, 2022). "Otherwise, TCAM1P promoted proliferation through regulating cell cycle and DNA replication, but more evidence needs to be provided to reveal the mechanism by which TCAM1P plays a role in cervical cancer." (PMID 35016697, 2022). "Cell function testing found that silenced the expression of TCAM1P in cervical cancer cell, the proliferation ability is significantly reduced." (PMID 35016697, 2022). "Results showed that the expression of TCAM1P in HPV16/18-positive cervical cancer is higher than in HPV-negative cervical cancer." (PMID 35016697, 2022). "To further determine the role of TCAM1P in cervical cancer, we once again analyzed its expression level in cervical cancer based on multiple GEO data sets and found that its expression in cervical cancer was higher than that in normal cervical tissue." (PMID 35016697, 2022). "To clarify the mechanism of high expression of TCAM1P in cervical cancer, we detected the expression of TCAM1P in the cytoplasm and nucleus." (PMID 35016697, 2022). "TCAM1P promotes the proliferation of cervical cancer cells and acts as promoter in cervical cancer." (PMID 35016697, 2022). "However, when we analyzed the prognostic value of TCAM1P in cervical cancer, we found that high expression of TCAM1P is related to good prognosis." (PMID 35016697, 2022). "Moreover, we verified the relationship between TCAM1P and HPV and confirmed that HPV E6/E7 and EIF4A3 can regulate the expression of TCAM1P, which promoted the proliferation of cervical cancer cells." (PMID 35016697, 2022). "TCAM1P was specifically high-expressed in normal testicular tissue and cervical cancer." (PMID 35016697, 2022). "First, we compare the expression level of TCAM1P between HPV-positive cervical cancer and HPV-negative cervical cancer based on GEO datasets." (PMID 35016697, 2022). "In order to further verify that the expression of TCAM1P is related to HPV infection, we used RT-PCR to detect the expression of TCAM1P in different cervical cancer cells." (PMID 35016697, 2022). "Considering that HPV 16 and HPV 18 were the most common and most carcinogenic infection type, we further analyzed whether there is a differential expression of TCAM1P in HPV16/18-positive cervical cancer and HPV-negative cervical cancer." (PMID 35016697, 2022). "In this study, we found that the AUC of TCAM1P for CIN 2 or CIN3 are as high as 0.901 or 0.840, which means that TCAM1P can effectively diagnose high-grade cervical lesions and can be an effective method for cervical cancer screening." (PMID 35016697, 2022).
cervical cancer (continued). "Besides, the expression of TCAM1P was HPV dependent, with highest expression in HPV-positive cervical cancer tissues." (PMID 35016697, 2022).
liver fibrosis (1 paper, 2022). "Interestingly, the CC genotype of rs2727324 (SMARCD2, TCAM1P) was associated with depletion of Bacteroides dorei and Marinifilaceae, which we previously reported as depleted in subjects with liver fibrosis in the CCHC." (PMID 36386790, 2022).
lymph node metastasis (1 paper, 2022). "Result showed that TCAM1P expression is higher in patients with Lymph node metastasis than in non-metastasis while the difference was not statistically significant in the remaining groups." (PMID 35016697, 2022).
cancer (1 paper, 2022). A tumor composed of atypical neoplastic, often pleomorphic cells that invade other tissues. "In this study, we firstly proposed that TCAM1P is cancer/testis pseudogene and is regulated by HPV E6/E7 and EIF4A3." (PMID 35016697, 2022). "Thus, in this study, we firstly proposed that TCAM1P is cancer/testis (CT) pseudogenes and is regulated by HPV E6/E7 and EIF4A3." (PMID 35016697, 2022). "TCAM1P acted as cancer/testis specific pseudogene need more data to explore its value." (PMID 35016697, 2022).
TCAM1P also shares sentences with these, for which no sentence is quoted: infection (2 papers); acute myeloid leukemia (1); hepatocellular carcinoma (1); testicular germ cell tumor (1).